FGFR1 (fibroblast growth factor receptor 1)
Diseases named in the same sentence as FGFR1 in open-access papers (continued):
Sharing a sentence is not in itself a finding about the gene and the disease.
breast cancer (continued). "FGFR1 amplification is also common in breast cancer, with approximately 15% of hormone receptor-positive patients and 5% of triple-negative breast cancer patients exhibiting amplification." (PMID 39583123, 2024). "About 3 in 4 breast cancers are estrogen-receptor positive (ER+) and within this group, an estimated 8–15% tumors exhibit FGFR1 amplification." (PMID 38553760, 2024). "FGFR1 amplification occurs in approximately 10% of breast cancers and functions to drive enhanced ligand-dependent signaling and suppress progesterone receptor expression, associated with poor prognosis." (PMID 38831455, 2024). "FGFR1 and KLHL6 mutations are protective factors for radiation-induced skin toxicity in breast cancer patients." (PMID 38380359, 2024). "More FGFR1 amplification and treatment-induced FGFR1 overexpression were found in patients with letrozole-resistant HR-positive breast cancer." (PMID 38255923, 2024). "Research indicates that both Dovitinib and Lucitanib exhibit significant inhibitory effects specifically in breast cancer patients with FGFR1 amplification, while sparing normal cells from adverse effects." (PMID 39590377, 2024). "FGFR1 amplification or overexpression is prevalent in various tumor types, with the highest rates observed in lung squamous cell carcinoma, breast cancer, bladder cancer, head and neck squamous cell carcinoma, and endometrial cancer." (PMID 39590377, 2024). "Several receptor-specific and pan-FGFR inhibitors have been developed and tested in clinical trials, either alone or in combination with other drugs; however, they showed little success in ER + breast cancers with FGFR1 amplification." (PMID 38553760, 2024). "TRPC1 silencing leads to reduction of Ca2+ signal mediated breast cancer process induced by FGFR1 activation." (PMID 38706904, 2024). "In ER + breast cancer, FGFs and FGFR1 amplification promote proliferation by activating MAPK signaling and increase cyclin D1 levels." (PMID 38553760, 2024). "This genetic alteration, along with FGFR1 overexpression, is a strong predictor of poor prognosis in ER + breast cancers." (PMID 38553760, 2024). "Specifically, FGFR1 amplification occurs in approximately 19% of lung squamous cell carcinoma cases, 10% of breast cancer cases, 14% of bladder cancer cases, 10% of head and neck squamous cell carcinoma cases, and 7% of endometrial cancer cases." (PMID 39590377, 2024). "In the cohort comprised breast cancer patients who received trastuzumab and pertuzumab, the pathological complete response rate was lower among those harboring FGFR1 amplification." (PMID 39193330, 2024). "FGFR1 amplification and overexpression also contribute to the resistance of breast cancer cells to the CDK4/6 inhibitors used in combination with endocrine therapy in either in vitro or in vivo patient-derived xenograft models." (PMID 38255923, 2024). "To investigate the role of FGFR1 in the regulation of p21 levels in ER + breast cancer cell lines, we used the pan-FGFR inhibitor TAS-120 (irreversible FGFR1-4 inhibitor) to block the effects of FGF2." (PMID 38553760, 2024). "We next analyzed the associations between FGF2 and FGFR1 gene expression levels and the expression of CDKN1A or CCND1 in the tumor transcriptomes of 601 ER + breast cancer patients from the Cancer Genome Atlas (TCGA)." (PMID 38553760, 2024). "This activation of the FGF2/FGFR1 signalling pathway promotes self-renewal and pluripotency of breast cancer stem cells." (PMID 40135140, 2024). "In a Phase 1/2a study of patients with breast carcinoma harboring an amplification of FGFR1, FGF3, FGF4, or FGF19, lucitanib resulted in a disease control rate (DCR) of 100%; 50% (6/12) of patients achieved PR and 50% (6/12) of patients had SD." (PMID 38380359, 2024). "In this study, we found that CAPE inhibits migration, invasion, and EMT of breast cancer cells through FGFR1 inactivation, including FGFR1 phosphorylation and nuclear transfer." (PMID 37490511, 2023).
breast cancer (continued). "Knockdown of FOXQ1 gene expression blocked the FGFR1 signaling-promoted breast cancer cell proliferation and colony formation in culture, and inhibited the FGFR1 signaling-accelerated growth in xenograft tumors derived from breast cancer cells in mice." (PMID 36778115, 2023). "FGFR2 is considered to be a susceptibility gene for breast cancer, FGFR4 is a driving factor for breast cancer, and FGFR1 overexpression is found in nearly 50% of breast cancer patients." (PMID 37490511, 2023). "Approximately 15% of breast cancers that are hormone receptor-positive and 5% of the more dangerous triple-negative breast cancers have been shown to have FGFR-1 overexpression, which is reported as frequent in breast cancer." (PMID 37446005, 2023). "But a study demonstrated that only 1 in 8 breast cancer patients with FGFR1 amplification responded to AZD4547 treatment." (PMID 37641116, 2023). "More recently ChIP-Seq of nuclear FGFR1 in breast cancer revealed that nuclear FGFR1 can regulate gene transcription and promote resistance to anti-oestrogen therapies." (PMID 36357571, 2023). "Although the prespecified efficacy target was met with an objective response rate of 19% in patients with FGFR1-amplified breast cancer, there was significant hypertension-related toxicity, limiting further development of the drug." (PMID 37980453, 2023). "Knockdown of FOXQ1 expression effectively prevented FGFR1-promoted breast cancer cell growth in culture and tumor growth in vivo." (PMID 36778115, 2023). "ER + breast cancer cells transduced with Fibroblast growth factor receptor 1 (FGFR1) was resistant to CDK4/6i." (PMID 37475713, 2023). "Further, in breast cancer, FGFR1-amplified cell lines express higher levels of FGFR1 protein and are more sensitive to FGFR inhibition with the pan-kinase inhibitor, brivanib, compared to cell lines with normal FGFR1 or FGFR1 deletion." (PMID 37130917, 2023). "Characterizing the specific downstream signaling pathways of FGFR1 and these pathway-regulated key genes responsible for mediating FGFR1-promoted breast cancer growth will help to identify alternative molecular targets for developing new therapies." (PMID 36778115, 2023). "For example, FGFR1 is amplified in lung and breast cancers and rarely in pancreatic and squamous cell lung cancers, whereas FGFR2 amplification mainly occurs in gastric and breast cancers." (PMID 38282676, 2023). "Consistent results were also obtained from MDA-MB-231 breast cancer cells with endogenous FGFR1 protein expression, in which the bFGF-induced FOXQ1 mRNA and protein expression can be blocked by MEK/ERK inhibitors but not by AKT inhibitors." (PMID 36778115, 2023). "Due to its role in paracrine signaling between epithelial cells and stromal fibroblasts that is emphasized in an ECM-dense environment, FGFR1 has been proposed as an MBD-related mediator in breast cancer development." (PMID 37546410, 2023). "Relative to other cancer types, FGFR aberrations are more frequent in breast cancer (18%), with FGFR1 amplification being the predominant aberration observed in 14% of breast cancer patients." (PMID 37546410, 2023). "In this study, we discovered that activation of FGFR1 signaling significantly upregulates the oncogenic transcription factor FOXQ1 through the FGFR1-ERK2-c-FOS gene regulatory axis in breast cancer cells." (PMID 36778115, 2023). "In contrast, the knockdown of FOXQ1 inhibited the role of FGFR1 signaling in the stimulation of breast cancer cell proliferation and colony formation in culture, as well as the growth of human breast cancer cell-derived xenografts in mice." (PMID 36778115, 2023). "In a different translational study of AZD4547, 341 patients were screened with fluorescence in situ hybridization; FGFR1 amplification was found in 18% of advanced HER2-negative breast cancers and 9% of advanced gastroesophageal cancers." (PMID 37980453, 2023).
breast cancer (continued). "In the present study, we found tumor-specific FGFR1 levels to be increased in 58% of the patients with early breast cancer compared with the corresponding FGFR1 levels in paired tumor-adjacent tissues." (PMID 37546410, 2023). "FGFR1 is a receptor tyrosine kinase deregulated in certain breast cancers (BCs) with a poor prognosis." (PMID 36778115, 2023). "FGFR1 is amplified in up to 15% of luminal breast tumors and has been shown to translocate to the nucleus of breast cancer cells, where it stimulates target gene expression." (PMID 37608351, 2023). "Since FGFR1 signaling upregulates FOXQ1 gene expression mainly through activating ERK2, we examined how the knockout of ERK2 or ERK1 affects FGFR1 signaling-promoted breast cancer cell growth." (PMID 36778115, 2023). "FGFR1 amplification is described as an early event in breast cancer initiation and dysregulated FGFR1 signaling is frequently occurring in breast cancer, and FGFR1 is a target for investigation in ongoing clinical trials for breast cancer therapy." (PMID 37546410, 2023). "MiR‐133b inhibits breast cancer cell growth and resistance to cisplatin by targeting FGFR1 to inactivate the Wnt/β‐catenin pathway." (PMID 37750089, 2023). "FGFR1 amplification or upregulation is frequently found in different types of tumors, such as breast cancer, non-small cell lung cancer, ovarian cancer, urothelial carcinoma, and hepatocellular carcinoma." (PMID 37591843, 2023). "Currently, FGFR1 activation has been shown to lead to increased cell proliferation, survival, and invasion both in mouse and human breast cancer cells." (PMID 37490511, 2023). "In other tumor entities such as non-small cell lung cancer or breast cancer, FGFR1 is frequently altered and a therapeutic target." (PMID 37733117, 2023). "Breast cancer cells expressing FGFR1, transduced with FGFR1 or amplified with FGFR1 were resistant to CDK4/6i." (PMID 37475713, 2023). "Although it is known that FGFR1 signaling can regulate many genes, the underlying molecular mechanisms and the key genes that mediate FGFR1-promoted breast cancer cell proliferation are still unclear." (PMID 36778115, 2023). "Taken together, these findings support a role of the FGF/FGFR1 system in early breast cancer which warrants further investigation in the MBD–breast cancer context." (PMID 37546410, 2023). "The overexpression of FGFR1 in lung and breast cancers has led to the development of drugs that target FGFR1 signaling and ligand binding." (PMID 37243023, 2023). "Overall, FGFR1-positivity was detected more frequently and at higher levels in breast cancer tissues compared with paired tumor-adjacent tissues." (PMID 37546410, 2023). "FGFR1 is frequently overexpressed in breast cancer, leading to endocrine therapy resistance as well as HER2 therapy resistance." (PMID 36900406, 2023). "In this study, we found that CAPE reduced the nuclear content of FGFR1 and showed a nuclear transfer inhibition of FGFR1 in breast cancer cells." (PMID 37490511, 2023). "Particularly, in breast cancer, FGFR1 amplification is found in 16–27% of luminal B-type breast cancer patients." (PMID 37591843, 2023). "FGFR2 amplification is less frequent than FGFR1 amplification across cancer types and is most often reported in patients with gastric-oesophageal junction adenocarcinoma and breast cancer." (PMID 37493315, 2023). "Recently, FGFR1 overexpression was shown to promote proliferation, invasion, and cancer cell stemness in MCF7 and T47D breast cancer cells, associated with phosphorylation and activation of ER." (PMID 37608351, 2023). "The FGF2/FGFR1 paracrine loop is functionally involved in the crosstalk between breast cancer cells and tumor stroma." (PMID 37445737, 2023).
breast cancer (continued). "Approximately 8–20% of breast cancers display FGFR1 amplification which correlates with early relapse and poor survival particularly in ER positive breast cancer." (PMID 35688802, 2022). "FGF4 promotes resistance to lapatinib in HER2-positive breast cancer cell lines through FGFR1 signalling, and FGF5 by inducing FGFR2 activation, which in turns transactivates HER2 and promotes resistance." (PMID 35193394, 2022). "Nuclear staining of FGFR1 has also been reported in breast cancer and pancreatic cancer, where this pattern has been associated with poor prognoses." (PMID 35053442, 2022). "This idea is in line with novel clinical strategies to treat breast cancer patients with multiple signalling inhibitors, including FGFR1–2." (PMID 35193394, 2022). "RTK families that have been shown to translocate to the nucleus include ErbB2 in breast cancer, FGFR1 in medulloblastoma, and VEGFR1 in lymphoma." (PMID 36214254, 2022). "Based on the Tumor Immunity Single Cell Center (TISCH) database, we revealed that FGFR1 is mainly expressed on fibroblasts in TME of breast cancer." (PMID 35832090, 2022). "FGFR1 nuclear localization in three-dimensional model of breast cancer and pancreatic cancer can influence the expression of hundreds of genes and contribute to migratory phenotype." (PMID 35488346, 2022). "Expression of fibroblast growth factor receptor-1 (FGFR-1) on tumor cells is a known mediator of endocrine treatment resistance and is associated with poor breast cancer patient outcomes." (PMID 35435599, 2022). "These examples illustrate the transforming ability of FGFR1 signalling in breast cancer cells and point to the FGFR1/MAPK signalling axis as a prominent drug target." (PMID 35193394, 2022). "Amplification of the FGFR1 gene is its most common variation, occurring in 8–15% of all cases of breast cancer." (PMID 35213975, 2022). "Here the authors report the results of a phase IIa study to assess the safety and efficacy of AZD454, an inhibitor of FGFR-1, 2 and 3 receptor tyrosine kinases, in combination with anastrozole or letrozole, in estrogen receptor positive breast cancer patients." (PMID 35688802, 2022). "We additionally compared the protein levels of Tie2 and FGFR1 in ECs, breast cancer cells, pericytes, and fibroblasts." (PMID 35884601, 2022). "8p11 is frequently amplified in breast cancer with a focal region co-amplifying FGFR1, 4EBP1, and WHSC1L1." (PMID 35626002, 2022). "Co-amplification of 4EBP1 and FGFR1 was significantly correlated with poor survival in breast cancer with a median survival of 94 months in 4EBP1 and FGFR1 amplified versus 115 months in non-amplified cases." (PMID 35626002, 2022). "FGFR1 amplification is the most frequent genomic alteration whereas FGFR2-4 amplification is relatively less common in breast cancer." (PMID 35846378, 2022). "This idea was confirmed by data showing that FGFR1 amplification was strongly associated with increased risk for distant disease in axillary node-, HR- and HER2-positive early breast cancer." (PMID 35193394, 2022). "We herein demonstrate that FGFR1 is relatively highly expressed in ECs, pericytes, and fibroblasts when compared to breast cancer cells." (PMID 35884601, 2022). "FGFR1 amplification is common in breast cancer (10%), predominantly in estrogen receptor-positive breast cancer, and harmful to the survival of patients." (PMID 35494629, 2022). "Using a more traditional phase 1 clinical trial design, futibatinib, an orally bioavailable, irreversible inhibitor of FGFR1–4 demonstrated an overall response rate of 13% across several solid tumour types, including breast cancer." (PMID 35193394, 2022). "As FGFR1 expressed on the cell membrane is closely related to the malignant biological behavior of breast cancer, an immunofluorescence assay was used to further determine FGFR1 levels." (PMID 35624697, 2022).
breast cancer (continued). "We present below an overview of the known roles of the FGF subfamilies and of FGFR1–4 in breast cancer progression and metastasis." (PMID 35193394, 2022). "The addition of VEGFR1 inhibitors solved the limited practical effects of FGFR inhibitors in FGFR1-amplified breast cancers through blocking the contribution of FGFR1 to VEGF secretion." (PMID 35494629, 2022). "In contrast, FGFR1 was comparably expressed in ECs, pericytes, and fibroblasts, but significantly lower expressed in breast cancer cells when compared to HUVECs." (PMID 35884601, 2022). "FGFR was also identified as a promoter to induce resistance to CDK4/6 inhibitors, which was diminished by complementary inhibition of FGFR in ER+/FGFR1-amplified breast cancers." (PMID 35494629, 2022). "Next, we measured the global translation levels using OP-puromycin-Cy5 labeling in breast cancer cells treated with FGFR1 and PI3K inhibitors." (PMID 35626002, 2022). "The description of a truncated FGFR1 (also referred to as nFGFR1) as a result of Granzyme B, was described in breast cancer cells and claimed to affect gene expression that altered cell behavior such as invasion." (PMID 35906694, 2022). "The first studies on the role of FGFR in breast cancer identified the amplification of FGFR1 and FGFR2 genes in human breast cancer samples." (PMID 35193394, 2022). "Activation of FGFR1 on breast cancer cells, as well as on stromal cells in the TME, initiates the production of the chemokine CX3CL1 (fractalkine) that recruits CX3CR1-expressing macrophages/monocytes to the TME." (PMID 35677046, 2022). "For instance, FGFR1 is recurrently upregulated in breast cancer, small cell lung cancer, pancreatic cancer, bronchoalveolar cancer, dysembryoplastic neuroepithelial tumor, and prostate cancer." (PMID 35683481, 2022). "Alterations in FGFR1 have been reported in 3.63% of all cancers, with breast carcinoma, non-small cell lung carcinoma, colorectal adenocarcinoma, malignant glioma and ovarian neoplasms showing the greatest prevalence of abnormalities." (PMID 35488346, 2022). "In breast cancer cell lines, GALNT14 O-glycosylation of FGFR1 primes breast cancer cells to respond to FGFR activation." (PMID 34068954, 2021). "In breast cancer, FGFR1 amplification represents the most frequent genomic aberration, mainly observed in the HR+/HER2- subtype." (PMID 33947144, 2021). "In particular, we previously reported that FGFR1 overexpression, which is more common in the luminal A and B subtypes of breast cancer, is an adverse outcome indicator for luminal A breast cancer, which is characterized by ER+/Her2-." (PMID 34831231, 2021). "Initially, FGFR1-expression-dependent differentially expressed pathways were identified using RNA-seq and microarray expression data of 1,425 breast cancer patients." (PMID 34722544, 2021). "Although MET is elevated in most basal breast cancer cell lines, we found that both FGFR1 protein and mRNA levels are preferentially enriched in basal B cell lines." (PMID 33772015, 2021). "A case report has shown activity in FGFR1-amplified breast cancer with the FGFR inhibitor pazopanib and erdafitinib has shown activity in FGFR-altered urothelial carcinoma." (PMID 33441174, 2021). "For 31 hormone receptor (HR)+/HER2− breast cancers, there were two clusters: One with the co-occurrence of ATM, FGFR1, and WT1 frameshift mutations, and the other with JAK3 splice site and FGFR2 frameshift mutations." (PMID 34203389, 2021). "In phase II clinical trials, dovitinib prolonged DCR and median PFS from 3% and 5.5 months to 25% and 10.9 months in patients with FGFR1‐amplified/HR‐positive breast cancer, respectively." (PMID 33655556, 2021).